EFNA3 (ephrin A3)
Diseases named in the same sentence as EFNA3 in open-access papers (continued):
Sharing a sentence is not in itself a finding about the gene and the disease.
colitis (1 paper, 2024). Inflammation of the colon. "A dextran sodium sulfate (DSS) model experiment with 5 wild-type and 5 Efna3 null-allele female mice found Efna3 null mice to be protected significantly (P < .0001) against colitis." (PMID 38369131, 2024). "Male Efna3 null-allele mice did not demonstrate a significant difference in DSS colitis severity compared with wild-type littermates (not shown)." (PMID 38369131, 2024).
colorectal cancer (1 paper, 2021). A primary or metastatic malignant neoplasm that affects the colon or rectum. "At the same time, the expressions of lnc-HOXC4-3:1, EFNA3, and LINC00520 were identified to be significantly related with the overall survival of colorectal cancer patients with P-values of 0.002, 0.008, and 0.021, respectively." (PMID 34262591, 2021).
ependymoma (1 paper, 2024). A WHO grade II, slow growing tumor of children and young adults, usually located intraventricularly. "In 2005, research identified the overexpression of ephrin-A3, ephrin-A4, EPHB2, EPHB3, and EPHB4 in ependymoma tumor cells, either from frozen or formalin-fixed tumor samples, but the clinical impact remains unclear." (PMID 38612645, 2024).
infarction (1 paper, 2020). A localised pathological necrosis of tissue resulting from obstruction of the blood supply usually by a thrombus, an embolus, or vascular torsion. "miRNA-210 has been shown to quell Efna3 at the level of transcription, allowing angiogenesis to ensue in post-infarction cardiac tissue." (PMID 33008044, 2020).
inflammatory bowel disease (1 paper, 2021). A spectrum of small and large bowel inflammatory diseases of unknown etiology. "In contrast, hematopoietic cell lineage, Staphylococcus aureus infection, intestinal immune network for IgA production, and inflammatory bowel disease pathways were negatively correlated with EFNA3 mRNA expression." (PMID 35126464, 2021).
ischemia (1 paper, 2014). A hypoperfusion of the BLOOD through an organ or tissue caused by a PATHOLOGIC CONSTRICTION or obstruction of its BLOOD VESSELS, or an absence of BLOOD CIRCULATION. "Another study confirmed EFNA3 as a direct target of miR-210 through luciferase assay, however, upregulation of EFNA3 was shown in ischemia brain, which seemed to be contradictory with the hypothesis that hypoxia induced miR-210 expression would result in downregulation of EFNA3." (PMID 24909053, 2014).
liver cancer (1 paper, 2024). An epithelial or non-epithelial malignant neoplasm that arises from the liver. "Particularly, several key genes, such as SLC27A5, IGF2, EFNA3, DCAF4L2, and SPP1, have been demonstrated to be associated with liver cancer." (PMID 39628446, 2024).
lung squamous cell carcinoma (1 paper, 2022). "The expression of EFNA1 was high in bladder urothelial carcinoma (BLCA), EFNA2 was highest in stomach adenocarcinoma (STAD), and EFNA3 was highest in lung squamous cell carcinoma (LUSC)." (PMID 35309935, 2022).
lung tumor (1 paper, 2018). "Furthermore, expression levels of the downstream markers of the corresponding microRNAs, namely PTEN, MARCKs, TPM-1, PDCD4, SPRY-2, ETS-1, ZEB-2, FGFRL-1, EFNA-3, and k-RAS were downregulated in the lung tumor lesions of patients with the underlying condition compared to non-COPD patients." (PMID 29371906, 2018). "However, expression levels of downstream markers TPM-1, TOM-1, CRK, fibulin-2, MIF, and EFNA-3 were greater in the lung tumors than in non-tumor specimens only in patients without COPD." (PMID 29371906, 2018).
Moyamoya disease (1 paper, 2013). Moyamoya disease (MMD) is a rare intracranial arteriopathy involving progressive stenosis of the cerebral vasculature located at the base of the brain causing transient ischemic attacks or strokes. "We identified 165 significantly (p < 0.05) elevated autoantibodies in Moyamoya Disease, including those against CAMK2A, CD79A and EFNA3." (PMID 23518061, 2013).
Obesity (1 paper, 2024). Accumulation of substantial excess body fat. "Therefore, in this study we determined the impact of maternal obesity in pregnancy on cortical, hippocampal development, vasculature and ephrin-A3/EphA4-signaling, in the adult offspring in mice." (PMID 38308309, 2024).
rectal cancer (1 paper, 2022). A primary or metastatic malignant neoplasm that affects the rectum. "The intersection of the candidate target genes in the MAPK pathway and the overexpressed genes in colon and rectal cancer in TCGA and GTEx was taken, and 5 candidate genes EFNA2, RPS6KA2, MAPK13, EFNA3 and FGFR3 were identified." (PMID 34998382, 2022).
tumor (49 papers, 2008 to 2026). "EFNA3 was consistently overexpressed across multiple cancer types and associated with tumor progression and poor survival." (PMID 42004975, 2026). "Ephrin A3 (EFNA3), similar to many genes within the ephrin family, holds a pivotal role in embryonic development and is susceptible to dysregulation in various tumour types." (PMID 38132457, 2023). "EFNA3 lncRNAs are transcribed from the EFNA3 locus which also encoded Ephrin-A3, a signaling ligand crucial for tumor metastasis and extravasation." (PMID 28789687, 2017). "Other members of the Eph receptor and ephrin families, including EphA2, EphB4, ephrin A1, and ephrin A3, have previously been implicated in radioresistance in different tumor models." (PMID 25879388, 2015). "Importantly, we found that EFNA3 was associated with the tumor microenvironment and lymphocytes." (PMID 34645436, 2021). "Both microRNAs were detectable in all tumor specimens to different extents and exhibited correlations with several hypoxia-associated molecular markers, such as miR-210 and, in the case of miR-155, components of the urokinase-like plasminogen activator (uPA) system and ephrin-A3 (EFNA3)." (PMID 32806571, 2020). "We also founded the higher level of EFNA3 was, the higher tumor malignancy degree of CM patients was." (PMID 38630320, 2024). "The prognostic and therapeutic value of EFNA3 in UM patients and other tumor types worth in-depth research." (PMID 38630320, 2024). "DNA methylation data showed that EFNA2 and EFNA3 positively correlated with tumor stemness in most cancers, whereas other family members revealed opposite results in various cancers." (PMID 35945523, 2022). "In contrast, EFNA3 contributes to tumor cell self-renewal, proliferation and migration in HCC under hypoxia via SREBP1/ACLY-mediated metabolic rewiring in HCC." (PMID 36052169, 2022). "The results indicated that EFNA2 expression correlated with tumor residue; the expression of EFNA3 and EFNA4 correlated with age; EFNA5 expression correlated with the number of pack-years smoked." (PMID 35945523, 2022). "High expression of EFNA3, EFNA4, and EFNB1 was associated with tumor progression and worse prognosis in HCC patients." (PMID 36052169, 2022). "In the tumor microenvironment and drug sensitivity, EFNA3/4/5 also showed a significant correlation." (PMID 35309935, 2022). "EFNA3 was upregulated in HCC tissues, and its overexpression was associated with more aggressive tumor behaviors." (PMID 36052169, 2022). "In Ephrin receptors, EFNA4 was conserved in EGFR-mut and KRAS-mut tumor while EFNA3 was conserved in EGFR-mut and NEK tumors." (PMID 36612014, 2022). "It was noted that EFNA3, a classic tumor suppressor, has 7mer-m8 molecular binding sites for miR-210, and previous studies have also reported that EFNA3 can be regulated by miR-210 in the nervous system." (PMID 36466111, 2022). "Further analysis revealed that the IHC score for EFNA3 was significantly upregulated in cases of larger tumor sizes, lymph node metastasis, and advanced TNM stage." (PMID 34645436, 2021). "Hypoxic BrCa cells 4T1 release miR-210-containing EVs in the tumor microenvironment resulting in inhibition of Ephrin-A3 and Protein tyrosine phosphatase 1B (PTP1B), as well as in the increase of angiogenesis and tumor proliferation." (PMID 34616676, 2021). "The relationships between the expression of EFNA3 and tumor-infiltrating lymphocytes (TILs) were analyzed by Spearman correlation using the TISIDB database." (PMID 34645436, 2021). "The chi-square test showed that EFNA3 protein expression was significantly correlated with larger tumor size (P = 0.004), lymph node metastasis (P = 0.035), and a higher TNM stage (P = 0.002)." (PMID 34645436, 2021). "In the tumor microenvironment, upregulation of ephrin-A2, ephrin-A3, EphB2, and EphB4, to name a few, on vascular cells in response to tumor factors has been the most well-studied." (PMID 31333644, 2019).
tumor (continued). "Exosomal miR-210 from lung cancer regulates the level of tyrosine receptor kinase A3 (ephrin A3) in matrix cells and promotes tumor angiogenesis to maintain the growth of tumor cells." (PMID 30217217, 2018). "Based on western blot analysis of tumor tissues, we confirmed that results were similar to IHC findings and showed that Ephrin-A3 and PTP1B protein levels were reduced in Exo (+) tumors, while VEGF was increased in Exo (+) tumors." (PMID 28038441, 2017). "The different role of EFNA3 in various tumor may be related to the distinct background of intracellular signaling networks." (PMID 38630320, 2024). "In xenograft tumor model, EFNA3 knockdown and ART significantly inhibited tumor growth." (PMID 38630320, 2024). "Ki67 the tumor proliferation index was decreased in knockdown EFNA3 and ART treatment group." (PMID 38630320, 2024). "Knockdown of EFNA3 inhibited CM cell proliferation and migration in vitro and tumor growth in vivo." (PMID 38630320, 2024). "In addition, overexpression of EFNA3 contributed to promoting tumour cellular activities, including cell proliferation, angiogenesis and invasion." (PMID 38009813, 2024). "Grange and colleagues performed molecular characterization of microvesicles and identified specific mRNAs associated with tumor progression and metastasis, including VEGF, fibroblast growth factor-2 (FGF2), angiopoietin-1 (ANGPT1), ephrin-A3 (EFNA3), metalloproteinase (MMP)-2, and MMP9." (PMID 37762660, 2023). "In brief, it can be concluded that high expression of EFNA3, EFNA4, and EFNB1 may be relevant to more gene mutations and, thus, drive oncogenesis and tumor progression of HCC." (PMID 36052169, 2022). "EFNA3 helps in proliferation, invasion of peripheral nerve sheath tumors, and tumor angiogenesis." (PMID 35945523, 2022). "Then, it was confirmed that miR-210 could regulate EFNA3 expression; further mechanistic analysis revealed that miR-210 could promote tumor progression via the PI3K/AKT/VEGFA or Wnt/Β-catenin/RHOA pathways." (PMID 36466111, 2022). "We discovered that EFNA3, EFNA4, and EFNB1 were highly expressed in HCC tissues compared with normal samples, and the high expression of these genes was associated with tumor progression and vascular invasion and, thus, led to poor prognosis in patients with HCC." (PMID 36052169, 2022). "Tumor specimens were divided into groups based on high and low EFNA3 expression." (PMID 35126464, 2021). "Hypoxia inducible factor caused Ephrin-A3 to gather on the cell surface by increasing the expression of lncRNA EFNA3 21, which induced tumor cells infiltration into surrounding tissues from blood vessels, thus promoting the invasion and metastasis of cancer cells." (PMID 33976738, 2021). "In addition, we investigated the relationship between EFNA3 and tumor infiltrating immune cells (TIICs)." (PMID 34645436, 2021). "Next, we assessed the correlation between EFNA3 expression and the tumor immune microenvironment." (PMID 34645436, 2021). "By in vitro and in vivo visualization, we found that exosomes with miR-210 were transferred to cells in the tumor microenvironment and that miR-210 was involved in expression of vascular remodeling related genes, such as Ephrin A3 and PTP1B, to promote angiogenesis." (PMID 28038441, 2017). "The role of EFNA3 in different tumors may be related to the tumor environment." (PMID 38630320, 2024). "Importantly, several studies have shown that EFNA3 is involved in tumor angiogenesis." (PMID 34645436, 2021). "Our results found EFNA3 boosted CM cells’ growth and migration through activating Stat3/Akt signaling pathway, while ART inhibited the tumor promoting effect of CM via downregulating EFNA3." (PMID 38630320, 2024). "As a result, we identified four membrane proteins—LRRC15, EFNA3, TSPAN13, and CA12—that demonstrated high expressions in BC tissues compared to adjacent non-tumor breast tissues and other healthy samples, with a few exceptions." (PMID 38611080, 2024).
tumor (continued). "We discovered that the size and weight of tumor in ART treatment group were smaller than control group and knockdown EFNA3 group." (PMID 38630320, 2024). "Our analysis consistently confirmed the increased expressions of LRRC15, EFNA3 TSPAN13, and CA12 in tumor samples, consistent with TCGA data findings from the DS and VS cohorts." (PMID 38611080, 2024). "Significantly, it was revealed that miR-210 exerts a negative regulatory effect on EFNA3 expression and actively participates in the PI3K/AKT/VEGFA or Wnt/β-catenin/RHOA pathways, thereby promoting tumour angiogenesis and cellular permeability." (PMID 38132457, 2023). "In HCC, the expression levels of EFNA1, EFNA3, EFNA4, EFNB1, and EFNB2 were significantly higher in tumor tissues than in normal tissues." (PMID 36052169, 2022). "The expression of EFNA1, EFNA3, EFNA4, EFNB1, and EFNB2 was significantly increased in tumor tissues compared with normal tissues." (PMID 36052169, 2022). "We found that the expression of EFNA1, EFNA2, EFNA3, EFNA4, EFNB1, and EFNB2 was upregulated in the tumor tissues of most cancers compared with corresponding normal tissues." (PMID 36052169, 2022). "As a consequence, pathological stage, residual tumor, and the expression of EFNA2, EFNA3, and EFNA5 had significant prognostic significance in LUAD." (PMID 35945523, 2022). "The expression of EFNA3 was evidently negatively related to stromal scores (R = −0.27, p = 2.1e-07) and ESTIMAT scores (R = −0.13, p = 0.0099) but positively related to tumor purity (R = 0.13, p = 0.0099) in HCC." (PMID 36052169, 2022). "Further mechanistic detection revealed that miR-210 negatively regulated EFNA3 expression and participated in the PI3K/AKT/VEGFA or Wnt/Β-catenin/RHOA pathways, thus promoting tumor angiogenesis and cellular permeability." (PMID 36466111, 2022). "In this study, we used the online tools Tumor Immune Estimation Resource (TIMER) and Gene Expression Profiling Interactive Analysis 2 (GEPIA2) to analyze the expression of EFNA3 in GC tissues." (PMID 35126464, 2021). "In this study, EFNA3, EFNB1, EFNB2, and EPHB2 showed a significant correlation with OS and PFS in LUAD patients and were differentially expressed in tumor tissues and normal lung tissues." (PMID 34645436, 2021). "In contrast, high EFNA3 predicted improved overall and progression-free survival in The Cancer Genome Atlas HGSC dataset, as expected for a canonical inducer of tumor-suppressive Eph receptor tyrosine kinase signaling." (PMID 33893375, 2021). "Then, TIMER was applied to evaluate the correlation between the expression levels of EFNA3 and SERPINE1 with tumor purity and infiltrating levels of immune cells." (PMID 34249015, 2021). "These pathways were all connected to tumor growth, and the PI3K/Akt signaling pathway (eight involved genes: CCND2, CDKN1B, CSF1, EFNA3, FGFR2, FGFR3, IL2RB, and ITGA9) ranked first among upregulated pathways (Enrichment Score = 3.159187)." (PMID 30755239, 2019). "Tumor expression of miR-210 significantly increased in LC-COPD compared to LC patients, while that of its downstream targets FGFRL-1 and EFNA-3 was reduced in the former patients." (PMID 29371906, 2018). "We found that transfer of exosomal miR-210 from hypoxic cells results in inhibition of miR-210 target genes, such as Ephrin-A3 and PTP1B, in neighboring cells in the tumor microenvironment." (PMID 28038441, 2017). "Although many genes were downregulated in GB-1 3D culture relative to the parental tumor (e.g. FGFR3, TGFβ1 and TYMP), certain genes were now upregulated (e.g. FGF2, ANGPT1 and EFNA3)." (PMID 26203665, 2015). "Ephrin A3 (EFNA3) and Ephrin B2 (EFNB2) are ligands of the eph receptor family that plays a major role in tumor remodeling." (PMID 18549507, 2008).
tumor (continued). "Interestingly, both LRRC15 and EFNA3 showed significant overexpressions in all subtypes, including TNBC, when compared to non-tumor breast tissue." (PMID 38611080, 2024). "The tumor suppressive genes of the NRGPI (suppressed in NRGPI-High subgroup), the E2F2 and EFNA3, were regulated by a group of 4 microRNAs (E2F2: hsa-miR-490-3p and hsa-miR-145-5p; EFNA3: hsa-let-7c-5p and hsa-miR-133a-3p)." (PMID 36389725, 2022). "In the screening cohort, the expression of SERPINE1 and EFNA3 in tumor tissues was up-regulated when compared with adjacent non-cancerous tissues and normal tissues (P < 0.05)." (PMID 34249015, 2021). "On the biological effect of ephrinA3 in oncogenesis, knocking out EFNA3 can promote the cellular viability and invasiveness of MPNST cells; hence, EFNA3 may serve as a tumor suppressor." (PMID 32695810, 2020). "They observed that exosomes containing miR-210 were transferred to cells in the tumor microenvironment and that miR-210 was involved in the expression of vascular remodeling related genes, such as Ephrin A3 and protein tyrosine phosphatase PTP1B, to promote angiogenesis in tumor-bearing mice." (PMID 30901915, 2019). "In short, these findings suggest that some ephrin genes (EFNA3, EFNA4, and EFNB1) are closely related to malignant biological behavior, such as tumor growth, vascular invasion and distant metastasis, and, thus, could be used as promising diagnostic and prognostic biomarkers in patients with HCC." (PMID 36052169, 2022).